SRC (SRC proto-oncogene, non-receptor tyrosine kinase)
Diseases named in the same sentence as SRC in open-access papers (continued):
Sharing a sentence is not in itself a finding about the gene and the disease.
tumor (continued). "The overexpression of WT PPP2R1A promoted tumor growth while W257G mutation increased cell migration through the SRC-JNK-c-Jun pathway." (PMID 27272709, 2016). "In order to define the mechanism(s) of action for PAG1 as a tumor suppressor, we performed Western blot analysis for c-SRC and associated downstream signaling pathways." (PMID 26993602, 2016). "SRC has also been shown to negatively regulate p27 and elevated levels of p27 cause arrest of tumor growth and apoptosis." (PMID 27472461, 2016). "SRC immunoreactivity or elevated protein and mRNA expression was associated with late onset, an advanced stage, deeper tumor extension and the presence of metastasis." (PMID 26460485, 2015). "On the molecular basis, SRC regulates multiple signaling cascades associated with tumor development and progression, including the focal adhesion kinase (FAK) pathway, the epidermal growth factor receptor (EGFR) pathway, and the Ras/ERK pathway." (PMID 25140799, 2014). "The high expression of both plasma membrane S1P1 receptor and cytoplasmic Y216 phosphorylated c-SRC or phosphorylated c-RAF-1 in the same tumor from ER+ breast cancer patients is associated with shorter recurrence time." (PMID 23316473, 2012). "In contrast with S1P1, high tumor nuclear expression of both c-SRC and S1P2 is associated with longer disease-specific survival time." (PMID 23316473, 2012). "Similarly, SRC is an oncogene whose overexpression or elevated activity is associated with HCC tumor progression and metastasis." (PMID 40283942, 2025). "Additionally, proteins associated with neoplasm invasiveness and metastasis (SRC, ALDOA, ACTB, MAPK1, and RAC1) and those mediating epithelial to mesenchymal transition (annexin A1, Hsp27) were upregulated in the LNM group." (PMID 41193833, 2025). "Furthermore, SRC activation has been discovered to involve multiple processes underlying tumor development and progression, including cell proliferation, migration, invasion, and metastasis." (PMID 36633714, 2023). "In addition, SRC expression was strongly and significantly associated with tumor recurrence (p = 0.002)." (PMID 31731442, 2019). "FAK and SRC signaling also promote angiogenesis and protease-associated tumor metastasis." (PMID 27472394, 2016). "In spite of the fact that SRC somatic mutations are rarely detected in human malignancies, aberrant Src activity, resulting from pathological deregulation, is a bad prognosis maker in epithelial tumors and has important roles during tumor development/progression." (PMID 34999732, 2022). "Similarly, nuclear p-SRC (Tyr419) was also significantly associated with shorter disease-specific survival (log-rank test, p = 0.043) with marked differences depending on the tumor site." (PMID 31731442, 2019). "Indeed, increased SRC kinase activity is associated with the metastatic potential of many tumor types and SRC has an important role in regulating focal adhesion and adherent junctions, which are the principal subcellular structures involved in cell adhesion, motility and invasion." (PMID 25762618, 2015). "SRC inhibition also attenuated immune evasion, enhanced anti-tumor immunity, and synergized with anti-PD-1 or gemcitabine/bisphosphonate therapies." (PMID 42244989, 2026). "Consistently, inhibitors of SRC improves tumor-specific CD8+ T cells functions in TME and sensitizes antitumor effects of anti-PD-1 therapy." (PMID 41728086, 2026). "Elevated tumor glycolysis attracts monocytes/macrophages via the ENSA-K63la/SRC-pS12/STAT3-pY705/CCL2 axis." (PMID 39883522, 2025). "While tumor-like cells showed low SRC, SRCIN1, and DAB2IP expression, SLA was predominantly expressed in these cells." (PMID 40917877, 2025). "To determine the right combination therapy for controlling NSCLC tumors, we assessed the effectiveness of combining AXL and SRC inhibitors in regulating tumor growth using human cell lines and an animal CDX model." (PMID 39941857, 2025).
tumor (continued). "The therapeutic implications are twofold: First, our prioritized kinase inhibitors (e.g., dasatinib) exhibit dual activity against both tumor-intrinsic SRC pathways and adipocyte-mediated inflammation." (PMID 41199823, 2025). "In PC, the genes ESR1 and SRC exhibited overexpression in tumor tissues, whereas IL1B and CTNNB1 showed reduced expression." (PMID 41186627, 2025). "Mechanistically, this immunosuppressive tumor microenvironment arises from N1-acetylspermidine efflux-dependent SRC signaling activation, which concurrently drives CCL1 macrophage polarization and CCR8 regulatory T-cell recruitment." (PMID 41293149, 2025). "Dual inhibition of AXL and SRC produced superior tumor growth inhibition (TGI ~70%) compared to either monotherapy." (PMID 39941857, 2025). "Collectively, these results suggest that tumor cell–derived lactate regulated the ENSA-K63la/SRC-pS12/STAT3-pY705 axis in TAMs." (PMID 39883522, 2025). "Senescent endothelial cells secrete exosomal SLC1A5, which is taken up by tumor cells and suppresses ferroptosis in tumor cells via the EGFR/SRC/YAP1/GPX4 pathway, thereby promoting gastric cancer progression." (PMID 40919170, 2025). "Our results support this claim by demonstrating the high expression of CD318 and increased association with SRC/FAK, which is a known oncoprotein involved in tumor invasion and metastasis." (PMID 40725832, 2025). "Mutation analysis also showed frequent alterations in PRKN (34%), OPTN (21%), PINK1 (28%), and SRC (15%), with implications for the tumor microenvironment." (PMID 39859167, 2025). "Our studies confirmed that dual inhibition of AXL and SRC led to enhanced cell death and reduced tumor growth in both in vitro and in vivo models." (PMID 39941857, 2025). "Organoid and xenograft studies confirmed Pae-mediated tumor growth inhibition and SRC downregulation." (PMID 40872629, 2025). "scRNA-seq revealed compartment-specific target localization: AKT1/ESR1 in tumor cells, SRC/IL6 in myeloid cells, and MTOR/HIF1A across stromal compartments." (PMID 40746726, 2025). "Synergistic inhibition of AXL and SRC led to significant tumor growth suppression in A549 mice xenografts." (PMID 39941857, 2025). "The expression of proto-oncogene SRC was significantly increased in tumor tissues compared with normal lung tissues." (PMID 40599804, 2025). "How far the uptake of other Syntenin‐dependent tumour molecules on sEVs, like for example, SRC, impacts downstream signalling, and thus also the migration of target cells, still needs further investigation." (PMID 40831280, 2025). "Our findings further associate both metabolites with infections, neoplasms, and hyperphagia, showing strong binding affinities to STAT3, HSP90AA1, CASP3, CASP8, and SRC targets." (PMID 41295287, 2025). "UMAP distribution showed that AKT1 and ESR1 were primarily expressed in tumor cells, SRC and IL6 were concentrated in the Myeloid subpopulation, while MTOR and HIF1A exhibited a broader distribution across multiple cell types." (PMID 40746726, 2025). "To further validate the role of these metabolites in the antitumor effect, we conducted molecular docking studies to explore the interactions between differential metabolites in P. crataegi and core tumor targets such as SRC, GAPDH, and CASP3." (PMID 40877012, 2025). "For example, AKT1 participated in seven biological processes, EGFR and STAT3 were involved in six, and SRC contributed to five biological processes, highlighting their essential roles in mediating the anti-tumor effects of steamed PJR." (PMID 41465428, 2025). "It suppresses GBM cell growth and prevents tumor invasion and metastasis by inhibiting SRC and SFK, key regulators in GBM." (PMID 40598793, 2025). "Bioinformatics analysis has shown that several proteins interacting with MES are strongly associated with tumor progression, including PAK1, TNF, SRC, and CDC25A." (PMID 40699726, 2025).
tumor (continued). "By enhancing PI3K activity and AKT phosphorylation, SRC promotes cell proliferation and survival while influencing the tumor microenvironment to support tumor growth and metastasis." (PMID 41017855, 2025). "Association of the expressions of SRC, JUNB, FOSB and PD-L1 as well as clinicopathological characteristics in tumor samples of KRAS-mutant NSCLC patients." (PMID 40599804, 2025). "Association of the expressions of SRC, JUNB and FOSB as well as PD-L1 expression in tumor samples of KRAS-mutant NSCLC patients." (PMID 40599804, 2025). "SRC inhibitors (DGY-06-116, dasatinib, and bosutinib) also exhibit synergistic effects with MRTX849 in eliminating various tumor cell lines carrying KRAS-G12C mutations." (PMID 39661665, 2024). "Recently, a previously undisclosed role has been also unveiled, indicating that the nuclear localization of paxillin acts as a transcription factor for SRC, leading to angiogenesis and tumor growth." (PMID 38903185, 2024). "This synergistic effect leads to significant activation of downstream signaling pathways such as MAPK and SRC, further promoting tumor growth and migration." (PMID 39727945, 2024). "We found that the sensitivity of the WASL, GRB2, SRC, and Tks4 gene expression set was high for both tumor types (0.96 and 0.99), but the specificity values were low." (PMID 39234565, 2024). "Activation of SRC, a serine/threonine kinase, can promote tumor development, cell proliferation, migration, and invasion." (PMID 39770551, 2024). "Nectin cell adhesion molecule 2 (NECTIN2), an upstream target of cytoskeletal regulation via SRC signaling, is an adhesion molecule that has been reported to play a role in tumor growth, metastasis and angiogenesis." (PMID 39085398, 2024). "SRC is a proto-oncogene, when a tumor occurs, SRC will show obvious distribution and shift in the cell, from cytoplasmic distribution to nuclear distribution." (PMID 38533261, 2024). "Increased SRC expression has been observed in advanced EC tissues, contributing to tumor metastasis." (PMID 38448739, 2024). "Of note, the recently developed selective SRC inhibitor eCF506 shows increased anti-tumor activity in TNBC models in vivo." (PMID 39390250, 2024). "The activated SRC pathway promotes tumor growth and invasion by stimulation of angiogenesis, invadopodia formation, and extracellular matrix degradation." (PMID 38356711, 2024). "Via establishing the c‐SRC and Bcl2 signaling pathways, miR‐34a blocks tumor proliferation and invasion and thus induces senescence." (PMID 38173189, 2024). "We conducted a comprehensive bioinformatic analysis to investigate the mRNA and protein expression levels of Tks4 and its associated partner molecules (CD2AP, GRB2, WASL, SRC, CTTN, and CAPZA1) across different tumor types." (PMID 39234565, 2024). "In osteosarcoma and colon cancer, a combination of SRC inhibitors enhances tumor sensitivity to DOX therapy." (PMID 39664567, 2024). "SRC is a crucial signaling molecule in the process of tumor survival and invasion progress, essential in the regulation and enhancement of cellular functions." (PMID 39771106, 2024). "STAT3-Y705 phosphorylation has been shown to be regulated by SRC kinases in cultured tumor cells, and Fyn is required for Stat3-PO activation in T-cell receptor signaling and T-cell differentiation." (PMID 39641161, 2024). "Dual targeting of ABL and SRC using ATP-competitive small-molecule inhibitors, such as dasatinib and bosutinib, has emerged as a promising anti-tumor therapy in hematological malignancies." (PMID 39089584, 2024). "Mechanistically, we show that ITGB1 signaling in SCLC tumor cells induced an EMT-like phenotype via FAK/SRC signaling and that ITGB1 fulfilled essential roles in intra- and extravasation of SCLC cells." (PMID 38775153, 2024). "Inhibit tumor growth; promote tumor apoptosis; the levels of p-SRC, p-EGFR, p-STAT3 and p-AKT are down-regulated." (PMID 39045282, 2024).
tumor (continued). "Accordingly, analysis of The Cancer Genome Atlas (TCGA) breast cancer data revealed that expression of FOXM1 and SRC mRNAs correlated positively in patients’ tumor samples, particularly in luminal subtypes." (PMID 36795481, 2023). "Epithelial tumor cells undergoing EMT become responsive to stimulation by the ligand PDGF and PDGF/PFGF-R can activate SRC and the subsequent tumor formation and metastasis." (PMID 37046850, 2023). "Subsequently, we also did the CCK-8 and Transwell assays to evaluate the tumor cell proliferation, migration/invasion abilities upon SRC downregulation." (PMID 36633714, 2023). "SRC-FAK signalling accelerates tumour invasiveness by regulating integrin-mediated cell adhesion, cell motility and ECM degradation." (PMID 37439249, 2023). "In all four xenograft models, triplet combinations resulted in statistically significantly improved tumor growth inhibition as compared to BRAF + EGFR or BRAF + SRC inhibitor doublets." (PMID 36759733, 2023). "Altogether, SRC activation induces a tumor survival mechanism that acts in parallel to both the MAPK and EGFR signaling axes in BRAFV600E CRC." (PMID 36759733, 2023). "SRC is overexpressed and/or activated in various human malignancies, implying that it plays a crucial role in tumour progression." (PMID 37439249, 2023). "We observed amplifications in chromosome arm 20q (chr20q) in 74/373 tumours (19.8%), which includes SRC, TOP1, BCL2L1, ZNF217, AURKA, GNAS and ARFRP1." (PMID 37666855, 2023). "The increased expression of SRC with higher tumor grading (G3) suggests its potential involvement in tumor aggressiveness and progression." (PMID 37623256, 2023). "The results revealed that SRC mRNA level was significantly upregulated in primary tumor tissues compared in normal tissues, and the TNBC patients showed overall higher SRC expression than the other BC subtypes, including Luminal and HER2 + subtypes." (PMID 36633714, 2023). "SRC is related to tumor suppressor factors, monocyte-macrophages and T cell chemokines by interacting with IL-15, colony stimulating factor 1 (CSF1), C-C motif chemokine ligand 5 (CCL-5), etc.." (PMID 36902024, 2023). "More importantly, in vivo xenograft experiments also displayed that SRC knockdown TNBC cells significantly attenuated the tumor growth and size, as well as the pulmonary localization ability compared to the control cells." (PMID 36633714, 2023). "SRC is a tyrosine kinase involved in multiple aspects of tumor development, including proliferation, migration, and angiogenesis." (PMID 38155968, 2023). "High BPTF can promote the chromatin accessibility within the promoter region of ENO2 and SRC, improving the glycolytic activity of tumor cells." (PMID 36967443, 2023). "In bladder cancer, activation of the SRC pathway by FGFR3 leads to resistance of tumor cells to FGFR inhibitors, such as infigratinib or erdafitinib." (PMID 37750089, 2023). "SRC-3 KO and control wild-type Tregs were isolated from the spleens of SRC-3d/d:Treg and SRC-3f/f female mice, respectively, and then injected Tregs (800K cells) into tumor-bearing SRC-3f/f female littermates." (PMID 37253006, 2023). "A variety of preclinical studies have also demonstrated that FYN/SRC inhibitors inhibit multiple tumor progressions." (PMID 36740671, 2023). "In contrast, SRC-3 KO Tregs in tumors from tumor-bearing SRC-3d/d:Treg female mice had significantly elevated expression of Ifng (~fivefold) compared with Tregs from the tumors in tumor-bearing SRC-3f/f female mice." (PMID 37253006, 2023). "SRC is a member of the tyrosine protein kinase family, which can regulate the apoptosis, proliferation, migration, invasion, and metastasis of tumor cells." (PMID 37900162, 2023). "The discovery of the SRC gene arose from research on a chicken tumor virus called Rous sarcoma virus." (PMID 37900162, 2023).
tumor (continued). "SRC is known to be involved in many cellular functions, including the promotion of tumor‐cell survival, motility, and invasion, through a rapid activation of focal adhesion kinase (FAK) contributing to cell migration and EMT." (PMID 36305167, 2022). "We show that in HCT116 cells simultaneous combination of MEK and SRC inhibitors can synergise to reduce cell viability in vitro and tumour growth in vivo." (PMID 34856074, 2022). "The binding of c-Met with its ligand initiates a series of intracellular signals including PI3K/AKT, Ras/MAPK, JAK/STAT, SRC, and Wnt/β-catenin, and promotes tumor development and progression." (PMID 35163327, 2022). "d16-HER2 is supposed to constitutively generate activated d16-HER2 homodimers on the tumor cell surface that phosphorylate and activate SRC (pSRC) kinase to enhance cell proliferation and tumorigenesis." (PMID 36276152, 2022). "KAN0441571C prevented phosphorylation of SRC, which should also be of significance for induction of tumor cell death." (PMID 36297673, 2022). "In vivo, trametinib treatment of mice‐bearing HCT116 tumours increased phosphorylation of SRC on Tyr419, and, when combined with AZD0424, inhibition of tumour growth was greater than with trametinib alone." (PMID 34856074, 2022). "Gene functionality assessment using siRNA screening showed that targeting SRC had an anti-tumour effect in OAC cells with the potential to enhance chemotherapy treatment." (PMID 35954391, 2022). "To examine the involvement of PAIP1 in SRC phosphorylation, closely related to tumor invasion and metastasis, we performed western blot in PAIP1 knockdown cells." (PMID 35153296, 2022). "Oncogenic overexpression or activation of SRC has been revealed to play essential roles in multiple events of BC progression, including tumor initiation, growth, metastasis, drug resistance and stemness regulations." (PMID 36581908, 2022). "Lastly, in CR-TNBC patient P942, the baseline PDX tumor (BTY14) had high phosphorylation on the shared pTyr sites of SRC, FYN, LCK, YES1, and FGR as well as SFK substrates such as tensin, SHIP-1 (INPP5D), AFAP1L2, paxillin, and PTK2." (PMID 36077757, 2022). "Typically, SRC-mediated p27 phosphorylation impairs the Cdk2 inhibitory action of p27 and thereby promotes the tamoxifen-resistance in BC cells, as well as the tumor progression in a mouse BC model." (PMID 36581908, 2022). "For example, SRC-mediated LATS1 phosphorylation abolished the tumor suppressor activity of LATS1 and induced tumorigenesis in a YAP-dependent manner in BC cells." (PMID 36581908, 2022). "Particularly SRC inhibition is suggested to enhance the efficacy of conventional therapies as the tumor stroma would even be beneficially targeted." (PMID 35155239, 2022). "In contrast, FAT1-knockout tumor cells were significantly more sensitive to the SRC inhibitor dasatinib and SRC/Bcr-Abl inhibitor saracatinib and the CAMK2 inhibitor KN93 as compared to FAT1 wild-type cells." (PMID 35965328, 2022). "This allows us to envision new therapeutic settings using SRC inhibitors to resensitize tumor cells to BRAFi and to improve therapeutic benefits with delayed relapses." (PMID 36305167, 2022). "We confirmed that trametinib treatment activates SRC in HCT116 tumours in vivo and that SRC activation is effectively inhibited using AZD0424 alone or in combination with trametinib." (PMID 34856074, 2022). "In the absence of NECTIN1, they switch to cell–matrix adhesion and migrate away by activating an integrin/FAK/SRC pathway, leading to tumor dissemination." (PMID 36229674, 2022). "The pretreatment with the selective inhibitor for SRC-family kinases PP2 blunted these effects induced by E2, indicating the involvement of ER/SRC on tumor formation in vitro." (PMID 33503805, 2021).